RHO (rhodopsin)
Diseases named in the same sentence as RHO in open-access papers (continued):
Sharing a sentence is not in itself a finding about the gene and the disease.
retinal degeneration (continued). "Subretinal injection of AAV-mirtron vector (i.e., AAV-M3.M5H.RHOM3/5R) in Nrl.GFP/+, RhoP23H/+ mice has been shown to induced rhodopsin mRNA replacement, which partially rescued retinal degeneration." (PMID 36840007, 2023). "The significant increase in the number of photoreceptors with the aberrant localization of rhodopsin in the retinal sections of adgrv1rmc22 larvae indeed supports the notion that defective ciliary protein transport may lie at the origin of ADGRV1-associated retinal degeneration." (PMID 37371069, 2023). "CRISPR-Cas9 engineered NRL-deficient ESC retinal organoids exhibit an abnormal number of photoreceptors expressing S-Opsin.AAV-delivered CRISPR-cas9 Nrl gene knockdown in RHO-P347S Rd10 mice prevents retinal degeneration." (PMID 36840007, 2023). "Rhodopsin is most sensitive to blue light at 470–480 nm and serves as a mediator of light-induced retinal degeneration." (PMID 36059433, 2022). "Subsequently, we will explain the impact that reversible phosphorylation has on the interaction of the arrestin–rhodopsin complex, complex internalization via endocytosis, and retinal degeneration." (PMID 36499010, 2022). "Several mutants, for example rdgC and norpA, affect the phosphorylation of rhodopsin and show severe retinal degeneration." (PMID 36499010, 2022). "Knockout of ATF6 in a P23H-KI model of RP impairs rhodopsin clearance and accelerates retinal degeneration and functional deficits." (PMID 35346303, 2022). "RHO serves as a mediator of light-induced retinal degeneration, and the amount of RHO available during light exposure determines the severity of the damage that rods suffer." (PMID 36059433, 2022). "The same conclusion was reached for norpA mutants, in which retinal degeneration was also significantly ameliorated by removing rhodopsin’s C-terminus." (PMID 36499010, 2022). "Recent studies have shown that robust rhodopsin degradation precedes retinal degeneration and the IRE1 signal transduction pathway remains activated even after photoreceptor degeneration plateaus." (PMID 35346303, 2022). "Representing 25% of dominant retinitis pigmentosa and 15% of all the retinal degenerations, the RHO gene encoding rhodopsin is among most frequently studied genes." (PMID 34778871, 2021). "A previous study showed that removal of one allele of Ahi1, which encodes a component of the ciliary gate complex, significantly increases RHO mislocalization and accelerates retinal degeneration in Nphp1gt/gt mice." (PMID 33961633, 2021). "The P347L rats generated in this study showed rapid postnatal retinal degeneration, possibly due to an overexpression of rhodopsin, prolonged activation of phototransduction, or activation of mislocalized opsin." (PMID 34088267, 2021). "There is evidence suggesting that increased levels of rhodopsin and/or mis-localised rhodopsin contributes to retinal degeneration, both in mammals and in flies." (PMID 33495354, 2021). "This is consistent with our previous results, showing that inhibition of VCP function strongly attenuates retinal degeneration in flies as well as in rodent models of RHO P23H." (PMID 33562020, 2021). "We found increased retinal degeneration and diminished rhodopsin protein levels in P60 Atf6−/−Rho+/P23H retinas compared to P60 Atf6+/−Rho+/P23H." (PMID 34381136, 2021). "Our current work proves that pharmacological inhibition of VCP can also delay retinal degeneration in the RHO P23H rat in vivo." (PMID 33562020, 2021). "Reduction of dietary vitamin A, a precursor of the chromophore 11-cis-3-hydroxyretinal, which binds to opsin to generate the functional rhodopsin, mitigates both aspects of the mutant phenotype, rhodopsin accumulation and retinal degeneration." (PMID 33495354, 2021). "Immunohistochemical analysis of blue and green cone opsins and rhodopsin was performed to determine if Nr2e3 therapy can restore opsin expression and thus provide a molecular reset in retinal degeneration models." (PMID 32123325, 2021).
retinal degeneration (continued). "Using an RNAi based approach, we now provide evidence, that silencing VCP expression in RHO P23H transgenic rat organotypic retinal cultures via Reverse Magnetofection can protect photoreceptor cell death and attenuate retinal degeneration in vitro." (PMID 33562020, 2021). "Mutations in several other genes such as GUCY2D, RHO, CRX, etc., are also associated with both dominant and recessive retinal degeneration, but the situation is a little different for them." (PMID 33681214, 2021). "The P23H rhodopsin knock-in (P23H-KI) mouse develops retinal degeneration that mirrors RP phenotype in patients carrying the orthologous variant." (PMID 34381136, 2021). "While it was shown that miR-155 is expressed by MPs under stress and contributes to the MP inflammatory response in retinal degenerations, our data suggests that miR-155 is also taken up by rhodopsin+ photoreceptors, particularly during degeneration." (PMID 33037565, 2021). "Our results support a model in which targeted expression of DHDDS-RNAi resulted in a unique pattern of retinal degeneration and a drastic reduction of Rh1 rhodopsin level." (PMID 34290587, 2021). "Reducing rhodopsin levels by raising animals in a carotenoid-free medium not only attenuates rhodopsin accumulation, but also retinal degeneration." (PMID 33495354, 2021). "We now report on the effect of sodium valproate on the conformational stability of heterologously expressed wild-type rhodopsin and a rhodopsin mutant, I307N, which has been shown to be an appropriate model for studying retinal degeneration in mice." (PMID 34069614, 2021). "First, we examined steady-state levels of rhodopsin in retinal protein lysates collected from Atf6+/−Rho+/P23H and Atf6−/−Rho+/P23H at P12, an age before morphological defects in photoreceptors or retinal degeneration emerges in Rho+/P23H mice." (PMID 34381136, 2021). "In fact, reducing rhodopsin levels by dietary intervention modifies the extent of retinal degeneration." (PMID 33495354, 2021). "Previous studies examined different methods to improve chaperone activity in treating retinal degeneration related to rhodopsin aggregation." (PMID 33107904, 2020). "Comparative histology was undertaken in Tulp1-/-, rhodopsin-/- (Rho-/-) and retinal degeneration slow-/- (Rds-/-) mouse retinas." (PMID 32655363, 2020). "Nevertheless, the P23H that escapes ER quality control and reaches the outer segment (OS) has detrimental effects on OS structure and pharmacologically enhanced traffic of P23H rhodopsin to the OS accelerated retinal degeneration." (PMID 32196553, 2020). "One study proposes a mechanism where rhodopsin misfolding ultimately contributes to retinal degeneration and the visual changes that are seen in both retinitis pigmentosa and Alzheimer’s disease." (PMID 32351353, 2020). "Retinal degeneration analysis revealed that along with the reduction of the electrical responses, LD also led to significant morphological changes, reactive gliosis, Rhodopsin translocation and photoreceptor cell death." (PMID 32242818, 2020). "Retinal accumulation of each reporter was measured in two models of retinal degeneration: the transducin γ-subunit knock-out (Gγ1-/-) and P23H rhodopsin knock-in (P23H) mice." (PMID 31826915, 2020). "Autophagy is necessary to maintain retinal integrity, and upon its impairment, retinal degeneration occurs in the fly eye, with rhodopsin accumulating in Rab7-positive compartments." (PMID 31834921, 2019). "Our current findings are limited to studies of retinal degeneration secondary to rhodopsin misfolding, a form of proteotoxicity in which the abnormal processing of rhodopsin results in chronic activation of the ERS and disrupted autophagy–proteasome balance." (PMID 31320609, 2019).
retinal degeneration (continued). "Although the SD-OCT findings related to retinal degeneration in rhodopsin P23H transgenic rats (lines 1 and 2) were previously reported, there have been no reports on retinal degeneration in S334ter rats except for the TD-OCT findings of S334ter rats (line 3)." (PMID 30581855, 2018). "The OCT findings of retinal degeneration in heterozygous rhodopsin P23H transgenic rats (line 1), retinal degeneration (rd) 10 and rd 12 mice, arrestin knock-out mice, and Royal College of Surgeons (RCS) rats have been reported." (PMID 29522537, 2018). "The excessive phosphorylation of the receptor would induce formation of stable arrestin-rhodopsin complexes, accumulation of which is known to enhance retinal degeneration." (PMID 30666186, 2018). "We previously reported the characteristic SD-OCT findings of retinal degeneration in Royal College of Surgeon's (RCS) rats with mertk gene mutations and the rhodopsin P23H (line 2) transgenic rats." (PMID 30581855, 2018). "In the present study, we characterized the SD-OCT findings observed during the processes of retinal degeneration in rhodopsin S334ter transgenic rats (line 4) in relation to the histological, ultrastructural, and ERG features." (PMID 30581855, 2018). "We used three different mouse models exhibiting distinct aetiology and pathophysiology of retinal degeneration—Rho−/−, Rd10 and RHO-P347S." (PMID 28291770, 2017). "Defects in any step of the trafficking procedures will result in rhodopsin mislocalization, abnormal rod OS formation and retinal degeneration." (PMID 29203866, 2017). "Characterization of the newly developed RP model indicates a similar retinal degeneration pattern as CBA/J, with a decreased apoptosis rate and rhodopsin loss." (PMID 28258056, 2017). "Transgenic Xenopus expressing rhodopsin glycosylation mutants (T4K and T17M) exhibit light-exacerbated retinal degeneration, as in humans." (PMID 28255526, 2017). "Future optimization of HDR in this system would benefit from a sgRNA that targets only a single rhodopsin gene in order to reduce the co-occurrence of retinal degeneration." (PMID 28761125, 2017). "However, later on, the mutant rhodopsin transported to the outer segment could cause problems by reducing the ability to regenerate pigment after light exposure, thereby initiating the progression of retinal degeneration." (PMID 27144303, 2016). "Conversely, ATF4 knockdown retarded retinal degeneration in 1-month-old T17M Rhodopsin mice and promoted photoreceptor survival, as measured by scotopic and photopic ERGs and photoreceptor nuclei row counts." (PMID 27144303, 2016). "Taken together, the present findings support a close link between retinal degeneration, ER stress, anti-oxidative defense, autophagy, and rhodopsin biosynthesis." (PMID 27144303, 2016). "Previous investigators have evaluated retinal degeneration using OCT in P23H heterozygous rhodopsin transgenic rats, in retinal degeneration (rd) 10 and rd12 mice, and in arrestin-1 knock-out mice was reported in detail." (PMID 27644042, 2016). "Two insults often underlie a variety of eye diseases including glaucoma, optic atrophy, and retinal degeneration—defects in mitochondrial function and aberrant Rhodopsin trafficking." (PMID 26176594, 2015). "Rhodopsin tends to mislocalize in a variety of retinal degeneration models, including the rds-/-, and we have shown that in cones, opsins mislocalized with some forms of mutant RDS." (PMID 26406599, 2015). "Through combining Rh1::GFP and ey-flp/hid technique, we can efficiently perform large scale screens for mutants of retinal degeneration and rhodopsin homeostasis." (PMID 26659849, 2015). "Transgenic animal models of RHO-adRP have been a common resource to investigate the cell signaling pathways that lead to photoreceptor cell death in this form of retinal degeneration." (PMID 25695253, 2015).
retinal degeneration (continued). "For example, over-expression of rhodopsin (in the Bouse transgenic animal) leads to retinal degeneration and abnormally large OS discs, while expression of 50% of rhodopsin (in the rho+/−) results in OSs that are virtually normal." (PMID 24897172, 2014). "Here we further explore the role of RDS/ROM-1 and rhodopsin in OS morphogenesis and retinal degeneration by generating and characterizing models expressing various amounts of these proteins." (PMID 24897172, 2014). "Previously, we have demonstrated that activation of the unfolded protein response (UPR) occurs during retinal degeneration in both the S334ter and P23H RHO rat models." (PMID 24378535, 2014). "Here, we investigated the therapeutic potential of arimoclomol for P23H rhodopsin-mediated retinal degeneration." (PMID 24853414, 2014). "The transgenic rhodopsin P23H mutant rat is an experimental retinal degeneration model that is widely used to study retinitis pigmentosa." (PMID 25278831, 2014). "If it does, then the mutant protein's ability to bind appropriately to its G-protein-coupled receptor, rhodopsin, would likely be impaired, and this would likely lead to the retinal degeneration phenotype." (PMID 24019744, 2013). "Increases in rhodopsin-phospho-Ser334 levels were observed, supporting the notion that changes in the regulation of the phototransduction cascade occur during retinal degeneration." (PMID 23901245, 2013). "The developing chicken retina and the rd1 and rhodopsin-GFP mouse models of retinal degeneration were used to investigate programmed cell death during retinal development and degeneration." (PMID 24244436, 2013). "Our results demonstrate that the mitochondrial μ-calpain and AIF pathway is involved in early-stage retinal degeneration in rhodopsin transgenic S334ter and P23H rats, and inhibition of this pathway shows curative potential for rhodopsin mutation-caused RP." (PMID 23951212, 2013). "Although overexpression of rhodopsin leads to retinal degeneration, our previous study showed that overexpression of RDS in wild-type retinas does not cause any negative effects and can improve OS structure and function in the rds+/− and rds−/− backgrounds." (PMID 23650562, 2013). "Intriguingly, in a mice model of inherited retinal degeneration, Müller glial cells also express rhodopsin." (PMID 23951079, 2013). "T17M RHO transgenic mice carry a mutated human rhodopsin transgene, the expression of which in retina leads to protein misfolding, activation of UPR and progressive retinal degeneration." (PMID 23646198, 2013). "The T17M RHO CHOP−/− retinas were characterized by more pronounced retinal degeneration even when compared to T17M RHO mice." (PMID 23646198, 2013). "The authors investigated the time course and molecular mechanisms of death and the rhodopsin phosphorylation occurring during retinal degeneration after exposure to continuous low-intensity light." (PMID 23901245, 2013). "Mutation of Tulp1, a member of the TULPs, in human and mice, exhibits retinal degeneration due to the mislocalization of rhodopsin." (PMID 24068974, 2013). "Using our transgenic mice we have now shown that ectopic expression of BBS protein can effectively restore sperm flagella formation, rescue obesity, and successfully restore rhodopsin trafficking in photoreceptor cells preventing retinal degeneration." (PMID 23554981, 2013). "Impaired lysosomal delivery of endocytosed rhodopsin and its degradation has been reported to trigger progressive and light-dependent retinal degeneration in Drosophila models." (PMID 23754968, 2013). "Impaired lysosomal delivery of endocytosed rhodopsin and its degradation trigger progressive and light-dependent retinal degeneration in phototransduction mutants." (PMID 23754968, 2013).
retinal degeneration (continued). "To test the effects of rhodopsin levels on retinal degeneration induced by P23H-rhodopsin, we chose to use an extensively studied, slowly degenerating mouse line that contains a genomic mouse P23H-rhodopsin transgene." (PMID 23185477, 2012). "In a recent study it was shown that autophagy is responsible for the degradation of activated rhodopsin in order to prevent retinal degeneration." (PMID 24710475, 2012). "In a recent study, it was reported that activated rhodopsin is degraded by autophagy in order to prevent retinal degeneration." (PMID 22567011, 2012). "It is known in Drosophila that activated rhodopsin is degraded in endosomal pathways in normal photoreceptor cells and that accumulation of activated rhodopsin in some mutants leads to retinal degeneration." (PMID 24710475, 2012). "Work in Xenopus laevis has shown that Rab8T22N (a dominant negative form of Rab8) and Rab8Q67L (a constitutively active form of Rab8) expression disrupts rhodopsin trafficking and leads to retinal degeneration, a common occurrence in human ciliopathies." (PMID 23351793, 2012). "Taken together, these results provide new evidence showing that the Ktub protein is required for mediating rhodopsin endocytosis and retinal degeneration." (PMID 23228091, 2012). "Photoreceptors are sensitive to changes in rhodopsin levels, and overabundance of this protein can lead to retinal degeneration in mouse models." (PMID 23077406, 2012). "The heterozygous rod opsin mouse (50% rhodopsin/rod) is similar to human E249ter carriers in that very slow, if any, retinal degeneration occurs over 90–120 days." (PMID 21785698, 2011). "The present study investigated the therapeutic potential of curcumin in treating retinal degenerations due to misfolded rhodopsin." (PMID 21738619, 2011). "Two different LV pseudotypes were tested using the VSVG and the Mokola envelopes, as well as two animal models of retinal degeneration: light-damaged Balb-C and Rhodopsin knockout (Rho-/-) mice." (PMID 21901134, 2011). "However, whether cell death was caused directly by rhodopsin mis-trafficking was still not entirely clear, inasmuch as Q344ter was expressed along with endogenous rhodopsin, and it was noted that over-expression of rhodopsin alone can cause retinal degeneration." (PMID 20532191, 2010). "We also present direct cellular biological evidence of rhodopsin accumulation in the cell bodies of photoreceptors, only in mutant backgrounds that undergo retinal degeneration." (PMID 19214218, 2009). "The Drosophila phototransduction pathway, mediated by the major rhodopsin (Rh1), has served as a model system for studying retinal degeneration." (PMID 19214218, 2009). "We show that retinal degeneration can also be induced in these genetic backgrounds after rhodopsin is endocytosed, suggesting that failure to degrade internalized rhodopsin in a timely manner triggers cell death of photoreceptor neurons." (PMID 19214218, 2009). "Genetically engineered null mutations in arrestin and rhodopsin kinase, prolonging light-activated rhodopsin signaling, also show similar physiological and cellular dysfunctions leading to retinal degeneration." (PMID 19672311, 2009). "Using mutants that are defective in late endosome to lysosome trafficking, we were able to show that rhodopsin accumulates in endosomal compartments in these mutants and leads to light-dependent retinal degeneration." (PMID 19214218, 2009). "The amplitude of fold-inductions were similar to those observed for proteoglycans and CD44 in other mouse models of retinal degeneration, namely rd1 (rodless retina), rds (retinal degeneration slow, rd2), and rhodopsin knockout (Rho−/−) mice." (PMID 19050768, 2008). "Furthermore, changes in the Rhodopsin levels have been shown to contribute to early events of retinal degeneration." (PMID 40137463, 2025).